PSEN1 (presenilin 1)
Diseases named in the same sentence as PSEN1 in open-access papers (continued):
Sharing a sentence is not in itself a finding about the gene and the disease.
Alzheimer disease (continued). "Familial early-onset Alzheimer's disease (EOAD) is a rare form of dementia often caused by autosomal dominant mutations in APP, PSEN1, or PSEN2." (PMID 40575115, 2025). "We investigated mutations linked to early-onset Alzheimer’s disease (EOAD), particularly in the APP, PSEN1, and PSEN2 genes, which affect amyloid-beta production and neuronal integrity." (PMID 40725212, 2025). "Familial Alzheimer’s disease (FAD) is caused by dominant missense mutations in amyloid precursor protein (APP) and presenilin-1 (PSEN1), the catalytic component of γ-secretase that generates amyloid β-peptides (Aβ) from the APP C-terminal fragment C99." (PMID 40723827, 2025). "Rare genetic variants in the APP and PSEN1 and PSEN2 genes have been reported as pathogenic causes of early-onset Alzheimer’s disease, but they account for less than 1% of all cases." (PMID 39810256, 2025). "Familial Alzheimer’s Disease (FAD) is primarily caused by mutations in the APP, PSEN1, and PSEN2 genes, which encode proteins critical to Aβ generation and clearance." (PMID 40529145, 2025). "Alzheimer’s disease is linked to several genetic mutations, including amyloid precursor protein (APP) and presenilin genes (PSEN1 and PSEN2) mutations that have been found to be the most common, leading to early-onset Alzheimer’s disease." (PMID 41007636, 2025). "The 5xFAD mice overexpress the human amyloid precursor protein (APP) containing three familial Alzheimer's disease (FAD) mutations, and human presenilin‐1 (PSEN1) with two additional FAD mutations." (PMID 41047765, 2025). "One of the first organoid models for Alzheimer’s disease was generated from mutated progenitor cells containing familial AD (fAD) mutations in the APP and PSEN1 genes, resulting in organoids presenting amyloid aggregation and hyperphosphorylated tau." (PMID 40244116, 2025). "Background/Objectives: Background: Early-onset Alzheimer’s disease (EOAD) is primarily inherited in an autosomal dominant pattern, with mutations in the APP, PSEN1, and PSEN2 genes being central contributors." (PMID 40149496, 2025). "Psen1 is an upstream regulator whose proteolytic cleavage is involved in Alzheimer’s disease, a neurodegenerative disease with high comorbidity with age." (PMID 41006292, 2025). "When the amyloid precursor protein/presenilin 1 mouse model of Alzheimer’s disease (AD) was subjected to a secondary inflammatory challenge with interleukin-1β (IL-1β), primed astrocytes developed exaggerated chemokine responses." (PMID 39463449, 2025). "Mutations in the genes encoding APP, Presenilin-1 (PSEN1), and PSEN2 result in early-onset Alzheimer’s disease (AD)." (PMID 40783385, 2025). "In this study, we compared brain tissues extracted from 32-week-old male wild-type mice and 5×FAD transgenic Alzheimer's disease model mice, which carry mutations in the amyloid precursor protein ( APP ) and presenilin 1 ( PS1 ) genes." (PMID 40150820, 2025). "Within a year of identifying PSEN1, another gene encoding the transmembrane protein PSEN2 was shown to have a substantial connection with Alzheimer’s disease." (PMID 40149496, 2025). "Familial Alzheimer’s disease (AD) arises from mutations in APP, PSEN1, and PSEN2, which lead to abnormal amyloid-beta production and plaque formation." (PMID 40559997, 2025). "To date, more than 200 unique PSEN1 gene mutations and 16 PSEN2 gene mutations linked to Alzheimer’s disease have been documented." (PMID 40426657, 2025). "A model of Alzheimer’s disease in green monkeys (Chlorocebus sabaeus) was generated through gene-editing technologies, specifically by deleting exon 9 of the PSEN1 gene." (PMID 40426657, 2025). "A rare form of Alzheimer's disease (AD) is genetically determined through autosomal dominant mutations in the APP, PSEN1, or PSEN2 genes." (PMID 40110659, 2025). "Our analysis of FAD mutations in PSEN1, PSEN2, and APP has focused exclusively on neurons, a key brain cell type affected in Alzheimer’s disease." (PMID 39754192, 2025).
Alzheimer disease (continued). "Among these DEGs, certain genes associated with Alzheimer’s disease were identified, including Amyloid Beta Precursor Protein (APP), Presenilin 1 (PSEN1), and Cathepsin D (CTSD)." (PMID 40243634, 2025). "PSEN1, PSEN2, and APP mutations cause Alzheimer’s disease (AD) with an early age at onset (AAO) and progressive cognitive decline." (PMID 39754192, 2025). "ADAD accounts for approximately 1% of Alzheimer’s disease (AD) cases and is caused by autosomal dominant mutations in the Amyloid Beta Precursor Protein (APP), Presenilin 1 (PSEN1), or Presenilin 2 (PSEN2) genes." (PMID 39828719, 2025). "The 5XFAD mouse is a well-characterized and aggressive model of early-onset Alzheimer’s disease, engineered to overexpress human APP and PSEN1 mutations associated with familial AD." (PMID 40313736, 2025). "Well-known mutations in APP, PSEN1, and PSEN2 genes are primary causes of autosomal dominant early-onset Alzheimer’s disease (EOAD)." (PMID 41465142, 2025). "PSEN1 and PSEN2 mutations have been linked with the Amyloid protein precursor in early-onset Alzheimer disease." (PMID 38741048, 2024). "Familial Alzheimer’s disease typically appears earlier in life and is caused by hereditary genetic mutations in amyloid precursor protein (APP), presenilin 1 (PSEN1), and presenilin 2 (PSEN2)." (PMID 38410184, 2024). "Familial Alzheimer's disease (fAD) is caused by autosomal dominantly inherited mutations in the amyloid precursor protein (APP) and presenilin 1 or 2 (PSEN1/2) genes." (PMID 38824433, 2024). "We recover known coding variant associations, including rare variants in genes linked to monogenic disorders such as PSEN1 and APP1 and Alzheimer’s disease, and SQSTIM1 and Paget’s disease." (PMID 39563277, 2024). "Presenilin-2 (PSEN2 on chromosome 1) is a homologous gene of presenilin-1 (PSEN1 on chromosome 14), which is a causative factor in autosomal dominant early-onset Alzheimer’s disease (EOAD)." (PMID 39273625, 2024). "Masitinib is a multi-kinase inhibitor that also inhibits fibroblast growth factor receptors and has been identified as a synaptoprotective agent in a dual amyloid precursor protein (APP)/presenilin 1 (PSEN1) mouse model of Alzheimer’s disease (AD)." (PMID 39598703, 2024). "Molecular and genetic studies in AD patients have identified three primary genetic mutations associated with Early-Onset Alzheimer’s Disease (EOAD), linked with genes encoding amyloid precursor protein (APP), presenilin 1 (PSEN1), and presenilin 2 (PSEN2)." (PMID 39000011, 2024). "Familial Alzheimer’s disease (fAD) is a rare, inherited form of AD often linked to mutations in the APP and presenilin 1 (PSEN1) and presenilin 2 (PSEN2) genes." (PMID 39684324, 2024). "The 3,4-dihydroxybenzoic acid reduced Aβ levels in the hippocampus and cerebral cortex of amyloid precursor protein (APP)/presenilin-1 (PS1) transgenic Alzheimer’s disease (AD) model mice." (PMID 39519743, 2024). "A patient with the PSEN1 E280A mutation and homozygous for APOE3 Christchurch (APOE3Ch) displayed extreme resistance to Alzheimer’s disease (AD) cognitive decline and tauopathy, despite having a high amyloid burden." (PMID 38571814, 2024). "APP/PS1 mice are double transgenic Alzheimer's disease (AD) model mice expressing human APP and presenilin 1 with familial mutations causing early disease onset." (PMID 38915938, 2024). "Although most cases of Alzheimer’s disease have a sporadic onset, familial Alzheimer’s disease is mainly caused by mutations in three genes: APP, presenilin 1 (PSEN1), and presenilin 2 (PSEN2)." (PMID 36672267, 2023). "Four genes have been identified to be associated with Alzheimer’s disease, namely, the amyloid precursor protein (APP) gene, the presenilin 1 (PSEN1) gene, the presenilin 2 (PSEN2) gene and the apolipoprotein E (ApoE) gene." (PMID 37362440, 2023).
Alzheimer disease (continued). "In contrast to late-onset Alzheimer’s disease, early-onset Alzheimer’s disease (EOAD) is often caused by autosomal-dominant mutations, specifically in APP, PSEN1, and PSEN2." (PMID 37341843, 2023). "The etiology of early-onset Alzheimer’s disease (EOAD) is associated with alterations in the production of amyloid beta (Aβ) species caused by mutations in the APP, PSEN1, and PSEN2 genes." (PMID 37108607, 2023). "Following this logic, the PSEN1 gene is of key importance, as it represents an overlapping gene between prion diseases and neurodegenerative disorders, including Alzheimer’s disease." (PMID 37048113, 2023). "The presenilin-1 (PSEN1) gene is crucial in developing Alzheimer’s disease (AD), a progressive neurodegenerative disorder and the most common cause of dementia." (PMID 37759801, 2023). "In our study, a blood-brain barrier crossing flavonol glycoside hyperoside was identified with anti-Aβ aggregation, BACE inhibitory, and neuroprotective effect in cellular or APP/PSEN1 double transgenic Alzheimer's disease mice model." (PMID 36821955, 2023). "Mutations in the presenilin-1 (PSEN1), presenilin-2 (PSEN2), and amyloid precursor protein (APP) genes have been commonly identified in early-onset Alzheimer's disease (EOAD)." (PMID 37051054, 2023). "For example, aldehyde dehydrogenase 2 family member (ALDH2) ameliorated cardiac systolic dysfunction in an amyloid precursor protein (APP)/presenilin 1 (PS1) murine model of Alzheimer’s disease by inhibiting ACSL4-dependent ferroptosis." (PMID 37372148, 2023). "In this study, we systematically explored the relationship between Alzheimer's disease (AD) and non‐pathogenic variants of APP, PSEN1, and PSEN2 in a total of 3557 individuals in a Chinese population." (PMID 36217304, 2023). "It has several types, with the early-onset variant presenting usually as a result of a genetic mutation in Alzheimer’s disease susceptibility genes, such as amyloid precursor protein (APP) or presenilin 1/2 (PSEN1/2)." (PMID 37834345, 2023). "A small proportion of patients with Alzheimer’s disease (AD) carry autosomal-dominant mutations in the APP, PSEN1, or PSEN2 genes (adAD)." (PMID 37131241, 2023). "Further, in the amyloid precursor protein/presenilin 1 (AAP/PS1) model of Alzheimer’s disease, IL-10 knockout mice exhibit decreased amyloid-β deposits in their hippocampus and cortex." (PMID 36992299, 2023). "Four probands (2.04%) bore P/LP variants in causative genes of other diseases, including two with spinocerebellar ataxia type 2 (SCA2), one with Alzheimer’s disease (AD) (PSEN1 p.Leu282Arg), and one with Perry syndrome (DCTN1 p.Tyr78His)." (PMID 37198191, 2023). "About 2% of Alzheimer’s disease (AD) cases have early onset (FAD) and are caused by mutations in either Presenilins (PSEN1/2) or amyloid-β precursor protein (APP)." (PMID 37257821, 2023). "Previous evidence indicates that 5′-flanking hypomethylation of PSEN1, a gene involved in the amyloidogenic pathway in Alzheimer’s disease (AD), boosts the AD-like phenotype in transgenic TgCRND8 mice." (PMID 37511434, 2023). "Mutations in the genes encoding amyloid precursor protein (APP), presenilin 1 (PS1), and presenilin 2 (PS2) proteins affect amyloid beta (Aβ) generation, leading to altered APP cleavage and the pathophysiology underlying Alzheimer’s disease (AD) progression." (PMID 37108607, 2023). "GRk3 also improved spatial learning and reduced memory deficits in an amyloid precursor protein (APP)/presenilin 1 (PS1) double transgenic mouse model of Alzheimer’s disease (AD)." (PMID 38139116, 2023). "This study aims to investigate sex and age differences in the characterization of periodontal bone tissue, immune state and cognitive function in amyloid precursor protein/presenilin 1(APP/PS1) murine model of Alzheimer’s disease (AD)." (PMID 37370108, 2023).
Alzheimer disease (continued). "Familial Alzheimer’s disease (FAD), caused by mutations in Presenilin (PSEN1/2) and Amyloid Precursor Protein (APP) genes, is associated with an early age at onset (AAO) of symptoms." (PMID 35365805, 2022). "Familial Alzheimer's disease (FAD) is caused by dominantly inherited mutations in APP, PSEN1 and PSEN2." (PMID 34319632, 2022). "PSEN1, the gene for Alzheimer’s disease, was induced in double-transgenic Gottingen minipig and triggered Met146Ile (PSEN1M146I) mutation." (PMID 36325365, 2022). "Amyloid precursor protein (APP), presenilin 1 (PSEN1), and presenilin 2 (PSEN2) are associated with autosomal-dominant early-onset Alzheimer's disease (AD)." (PMID 36555832, 2022). "Mutations in the tau gene (MAPT) lead to frontotemporal dementia (FTD), whereas mutations in the genes for the amyloid-β precursor protein (APP) and the presenilins (PSEN1, PSEN2) cause early-onset, dominantly inherited forms of Alzheimer’s disease (AD)." (PMID 35120450, 2022). "Transgenic mouse models of Alzheimer’s disease (AD) overexpress mutations of the human amyloid protein precursor (APP) and presenilin-1 (PSEN1) genes, which are known causes of amyloid pathology in familial AD." (PMID 35163801, 2022). "Along with mutations in PSEN1 and PSEN2, APP is one of the most studied genes known to cause Alzheimer’s disease." (PMID 36175824, 2022). "In this review, we discuss the functions of PSEN1 in Alzheimer’s disease and its possible impact on other diseases." (PMID 36142879, 2022). "Mutations in genes encoding presenilin 1 or 2 (PSEN1 or PSEN2) and amyloid precursor protein (APP) have been linked to early-onset Alzheimer’s disease." (PMID 36077172, 2022). "This strain overexpresses both human Aβ precursor protein with the Swedish (K670N, M671L), Florida (I716V), and London (V717I) Familial Alzheimer’s Disease (FAD) mutations and human presenilin-1 harboring two FAD mutations, M146L and L286V." (PMID 35203488, 2022). "Genes of the GSC have an established role in the pathogenesis of both monogenic Alzheimer disease (primarily PSEN1) and familial HS (primarily NCSTN), although genetic studies of HS are still in their infancy and characterized by relatively small numbers." (PMID 36118898, 2022). "Mutations in the APP, Presenilin 1 (PSEN1), and Presenilin 2 (PSEN2) genes are known to be a cause of early-onset forms of Alzheimer’s disease, termed familial Alzheimer’s disease (fAD)." (PMID 35013145, 2022). "Monogenic forms of Alzheimer’s disease (AD) have been identified through mutations in genes such as APP, PSEN1, and PSEN2, whilst other genetic markers such as the APOE ε carrier allele status have been shown to increase the likelihood of having the disease." (PMID 36175824, 2022). "The established causative mutations in the APP, PSEN1, and PSEN2 can explain less than 1%,Alzheimer’s disease (AD) patients." (PMID 35491795, 2022). "A mutation in the Presenilin 1 (PSEN-1) gene, which is responsible for the majority of familial cases of Alzheimer's disease (AD), was corrected in iPSCs generated from a 58-year-old patient." (PMID 36939776, 2022). "An exciting application of the use of mouse panels in translational research comes from crossing the classical Alzheimer’s disease (AD) mouse model (5XFAD) bearing mutations in APP and PSEN1 with 28 different strains of the BXD panel (AD-BXD)." (PMID 35886916, 2022). "Mutations in the genes for the amyloid-β precursor protein (APP) and the presenilins (PSEN1 and PSEN2) cause early-onset, dominantly inherited forms of Alzheimer’s disease (AD), whereas mutations in the MAPT gene mainly lead to frontotemporal dementia (FTD)." (PMID 35120450, 2022). "Their findings have revealed the dysregulation of genes for amyloid protein precursor, β-secretase, presenilin 1 and 2, tau protein, autophagy, mitophagy, and apoptosis identical in nature to Alzheimer’s disease." (PMID 33671097, 2021).
Alzheimer disease (continued). "In particular to the genetic mutation observed in APP, PSEN1, or PSEN2 genes that are associated with early onset of Alzheimer’s disease (EOAD)." (PMID 34884789, 2021). "PSEN1 is a primary component of the γ-secretase complex, which is mainly related to Alzheimer's disease." (PMID 34335753, 2021). "We conclude that as reported in microglia in the APP/PS1 (amyloid precursor protein/presenilin 1) murine model of Alzheimer’s disease, upregulation of Ripk1 in both twitcher and SD mice, predominantly occurs in activated macrophage/microglia." (PMID 34172992, 2021). "For autosomal dominant early-onset Alzheimer's disease (EOAD), mutations in the APP, presenilin 1 (PSEN1), or presenilin 2 (PSEN2) gene sequence are a major risk factor, while the APOE4 allele is a major risk factor for late-onset Alzheimer's disease (LOAD)." (PMID 34122554, 2021). "Autosomal dominant Alzheimer’s disease (ADAD), caused by mutations in presenilin 1/2 (PSEN1/2) or amyloid precursor protein (APP), is a valuable model for characterizing the molecular drivers of Alzheimer’s disease." (PMID 33892504, 2021). "In a mouse model for Alzheimer disease (APP/Presenilin 1 mice expressing human mutant presenilin 1 and a chimeric mouse/human amyloid precursor protein (Mo/HuAPP695swe)) unilateral nephrectomy increased plasma and brain Aβ deposition and reduced Aβ in urine." (PMID 34204545, 2021). "As part of these efforts, we also utilized XMAS-TREE to enrich for cells that have been edited at several disease-relevant loci including those associated with sickle-cell anemia (i.e., HBG1, HBG2) and Alzheimer’s disease (i.e., AKAP9, PSEN1)." (PMID 33317513, 2020). "The model carries three mutations related to familial Alzheim’s disease (FAD): APP Swedish, MAPT P301L, and PSEN1 M146 V." (PMID 31987051, 2020). "Apart from that, a familial form of Alzheimer’s disease is also known, which is related to mutations in amyloid precursor protein (APP), PS1 presenilin 1 (PS1), and presenilin 2 (PS2) genes." (PMID 33374338, 2020). "Several genetic mutations have been identified in genes namely, APP, presenilin 1/2 (PS1/2), and APOE, to cause Familial Alzheimer’s disease." (PMID 33328842, 2020). "In our previous studies, we found gene expression changes associated with Alzheimer’s disease in the hippocampal CA1 region, such as β-secretase, presenilin 1 and 2, amyloid protein precursor, and tau protein during 2–7 days after brain ischemia." (PMID 31713815, 2020). "These anthocyanins also prevented apoptosis and neurodegeneration by suppressing the apoptotic and neurodegenerative markers in the amyloid precursor protein/presenilin-1 (APP/PS1) mouse model of Alzheimer’s disease (AD)." (PMID 32887513, 2020). "These reductions were significant with FC for 5 genes critical to Alzheimer’s disease (AD): Apbb1, ApoE, Mapt (Tau), Psen1, and Prnp." (PMID 32561719, 2020). "Alzheimer’s disease is caused by a mutation in the APP gene, or in the presenilin 1 (PSEN1) and 2 (PSEN2) genes." (PMID 29879811, 2019). "Such a model is the 5X familial Alzheimer’s disease mouse (5XFAD), which carries three disease-associated variants in APP and two disease-associated variants found in PSEN1." (PMID 30953144, 2019). "In the KEGG disease database, APP and PSEN1 are identified as representative genes for Alzheimer's disease." (PMID 31017923, 2019). "Presenilin 1 (PSEN1), presenilin 2 (PSEN2), and amyloid precursor protein (APP) mutations are responsible for autosomal dominant early-onset Alzheimer’s disease (AD-EOAD)." (PMID 31440394, 2019). "In human neuronal models of monogenic Alzheimer’s disease, APP and PSEN1 mutations disrupt lysosome function and autophagy, leading to impaired lysosomal proteolysis and defective autophagosome clearance." (PMID 30590039, 2018).